PRRX1 (paired related homeobox 1)
Diseases named in the same sentence as PRRX1 in open-access papers (continued):
Sharing a sentence is not in itself a finding about the gene and the disease.
tumor (continued). "PRRX1 overexpressed in MPNSTs directly interacts with topoisomerase 2 A (TOP2A) to cooperatively promote epithelial-mesenchymal transition and increase expression of tumour malignancy-related gene sets including mTORC1, KRAS and SRC signalling pathways." (PMID 38448751, 2024). "Prrx1 enhances the acquisition of stemness in non-stem tumor cells and maintains GSC stemness by promoting CD133 and SOX2 expression through activation of TGFβ pathway." (PMID 36635261, 2023). "In addition, this disparity became more obvious with the progression of tumor stage, suggesting a potential function of IL1RN and PRRX1 in tumor development and migration." (PMID 36483329, 2022). "In addition to collagens, the ECM of PDAC is composed of TNC and POSTN, which we have previously identified as downstream targets of Prrx1, which fosters liver metastasis in PDAC; therefore, they can be considered key molecules in tumor progression." (PMID 35000025, 2022). "PRRX1 is closely related to the occurrence of EMT, and it is an important transcription factor regulating EMT, which plays an important role in tumor recurrence and metastasis and tumor stemness maintenance." (PMID 35530319, 2022). "In the absence of the tumor microenvironment, Zeb1/2 levels were unaffected by Loxl3 silencing in MeL3 cells, although both gene and protein levels of Snail1 and Prrx1 EMT-TFs were markedly downregulated." (PMID 35267510, 2022). "Upon Kaplan-Meier overall survival (OS) analysis, we found a tendency towards improved outcome for patients with high PRRX1-expressing tumours, but this was not statistically significant." (PMID 34496784, 2021). "One of two major isoforms of PRRX1, PRRX1b promotes EMT (de-differentiation), invasion, and tumor differentiation while PRRX1a stimulates mesenchymal to epithelial transition (MET) (re-differentiation), metastatic outgrowth as well as tumor differentiation." (PMID 33572223, 2021). "In addition, in vivo studies showed that PRRX1+ MES cells increase in relapsed tumours and tumours treated with conventional chemotherapy." (PMID 34884690, 2021). "In mouse models, fibroblast-specific Prrx1 deletion led to more differentiated, less metastatic tumours, alongside changes to the tumour ECM, and this phenotype was attributed to release of hepatocyte growth factor (HGF) driving EMT in tumour cells." (PMID 34638468, 2021). "CAFs expressing Prrx1 could promote EMT and chemotherapeutic resistance in tumor cells through paracrine HGF signaling." (PMID 34646829, 2021). "Prrx1 potentiated stemness acquisition in non-stem tumor cells (NSTCs) and stemness maintenance in GSCs, accompanied with increased expression of stemness markers such as SOX2." (PMID 34131109, 2021). "Additionally, another less-reported TF known as paired-related homeobox 1 (PRRX1) also plays important role in tumorigenesis and promotes tumour invasion." (PMID 34868979, 2021). "Moreover, PRRX1 is a vital gene in EMT process and plays an extremely important role in tumor proliferation and metastasis." (PMID 32811812, 2020). "Although Prrx1+ MSCs located at different places including the periosteal bones have tri-lineage differentiation potentials, no tumor contains both chondrocytes and osteoblasts in Prrx1-CreERT; Ptch1f/f mice." (PMID 31482846, 2019). "It is predicted that tumors derived from multipotent MSCs would contain both osteoblasts and chondrocytes, yet no such tumor was detected in Prrx1-CreERT; Ptch1f/f mice." (PMID 31482846, 2019). "This phenotype would have mesenchymal features, that would result as a downstream effect of the STAT3-RAS-MAPK-ERK-MYC pathway, regulating ID3/E47 interactions and promoting tumor cell migration and invasion through expression of mesenchymal genes such as MMPs, SNAIL1, TWIST1, and PRRX1." (PMID 30899759, 2019).
tumor (continued). "In addition, three genes, MAP1LC3A, PRRX1 and SYT11, were moderately downregulated in the tumor tissues." (PMID 25789025, 2015). "Furthermore, STAD tumor samples exhibited significantly higher expression levels of PRRX1 compared with nontumor tissues." (PMID 40114375, 2025). "Using GO and KEGG functional enrichment analyses, we found that hub genes are involved in tumor immunity in their functions, so we performed an immunobioinformatics database search of 15 key genes to identify potential immune infiltration marker roles of IL1RN and PRRX1." (PMID 36483329, 2022). "Prrx1-expressing CAFs induced significant and consistent gene expressional changes in cancer cells; they increased gene expressions related to poor prognoses, such as EMT and metastasis, cancer stem cell phenotype, chemotherapy resistance, tumor cell proliferation, invasion, and glycolysis." (PMID 35589735, 2022). "Thus, PRRX1 is more often positively correlated with ZEB1 and ZEB2 in patients’ HCC tumour samples." (PMID 34496784, 2021). "Recent studies reported that tumor cells may undergo MET, the reverse process of EMT, to colonize distant organs, which is induced by downregulation of the EMT-inducing transcription factors Twist1 and Prrx1." (PMID 29416649, 2018). "We then assessed whether the in vitro chemotherapeutic effects of Mettl3 deletion in BMMSCs would translate into a tumor response in vivo by intravenously injecting 2 × 105 MLL-AF9 AML cells into nonirradiated Prrx1-CreERT2;Mettl3fl/fl mice and Mettl3fl/fl mice to establish a systemic AML model." (PMID 38052820, 2023). "Additionally, as Prrx1 is an inherently lineage-specific mTF, targeting Prrx1 may not interfere with other tumor-suppressive subsets of CAFs." (PMID 35589735, 2022). "Importantly, although our mouse models identify Prrx1-expressing cells as a source of FUS-CHOP-driven tumors, cells expressing PdgfRα cannot be ruled out as a potential tumor-initiating cell for FUS-CHOP-driven tumors." (PMID 31427882, 2019). "Notably, Prrx1-deleted CAFs [MMTV-CAFs (sgPrrx1)] did not increase the spheroid formation when they were cocultured with tumor cells (168FARN-Luc-GFP), suggesting that Prrx1 is vital for the tumor-promoting activity of CAFs." (PMID 35589735, 2022).
cancer (70 papers, 2014 to 2025). A tumor composed of atypical neoplastic, often pleomorphic cells that invade other tissues. "Recent studies indicated that PRRX1 TF controls the phenotype of a subset of cancer-associated fibroblasts promoting tumour growth and survival." (PMID 40856011, 2025). "The HD transcription factor PRRX1 plays a pivotal role in mesodermal development and is implicated in various cancers." (PMID 40114375, 2025). "By analyzing the International Cancer Genome Consortium (ICGC) database, a series of mutation sites on PRRX1 were identified in patients with various cancers." (PMID 40114375, 2025). "The epigenetic activity of transcription factor motifs linked to cancer immunogenicity, e.g., Irf1/2/8/9, Stat1, and Nfkb1, were increased in KO cells, which coincided with findings in a PRRX1-overexpressing cell line model." (PMID 39255035, 2024). "In previous studies, it was suggested that PRRX1 is a master transcription factor of myofibroblastic cancer-associated fibroblasts." (PMID 39010054, 2024). "The core promoter mutation in GAB2 and PRRX1 occurred at simple repetitive sequences, caused their altered expression in cancer." (PMID 35033028, 2022). "Univariable Cox regression analysis was performed to assess the association of PRRX1 expression levels with OS in patients with various types of cancer in 33 TCGA cohorts." (PMID 35281030, 2022). "PRRX1 expression in cancer-associated fibroblast (CAF) has an unfavorable prognosis in multiple cancer types." (PMID 35589735, 2022). "Here the authors identify PRRX1 as a master transcription factor determining a fibroblast lineage with myofibroblastic phenotype, associated with unfavourable prognosis in several cancer types." (PMID 35589735, 2022). "The authors further demonstrated that loss of PRRX1 is required for the cancer cells to metastasize, whereby the cells regain epithelial characteristics needed to form colonies at the secondary site." (PMID 34708244, 2022). "On the contrary, HOX member PRRX1 has the capacity to completely reactivate the epithelial state, even in the presence of TWIST1, and the loss of PRRX1 granted cancer cells the ability to colonize lungs." (PMID 34063254, 2021). "Based on our in silico analyses of several HCC patient gene expression datasets, which linked PRRX1 to metabolism and cancer pathways, we first focused on its influence towards cellular plasticity and EMT." (PMID 34496784, 2021). "Although the precise roles of PRRX1 and its isoforms, PRRX1a and PRRX1b, are unclear in human cancer, PRRX1 was often associated with cancer stemness and epithelial-mesenchymal transition (EMT)." (PMID 34496784, 2021). "In cancer, highSnail1 expression is associated with malignant phenotype and poor prognosis, while the high expression of Prrx1 is associated with good prognosis and metastasis-free disease." (PMID 31712603, 2019). "Here, we report that Twist1, a key regulator of cancer-associated fibroblasts, directly upregulates Prrx1, which, in turn, increases the expression of Tenascin-C (TNC)." (PMID 30069061, 2018). "A recent study demonstrated that downregulation of paired related homeobox 1 (PRRX1) is associated with the acquisition of cancer stem cell (CSC)-like properties and poor prognosis in HCC patients." (PMID 27119349, 2016). "PRRX1 has been also implicated in a positive feed-back loop in which TWIST1 directly increased PRRX1 which subsequently induced Tenascin-C that itself stimulated TWIST1 activity in Cancer associated fibroblast (CAF), and in dermal and fetal Human lung fibroblast lines." (PMID 37261432, 2023). "PRRX1-deficient A549 cells were further shown to acquire cancer stem cell-like properties." (PMID 34708244, 2022). "Moreover, PRRX1 loss‐mediated MET also confers cancer cells with stemness, leading to drug resistance thus further explaining why PRRX1 overexpression predicts good prognosis." (PMID 35601657, 2022).
cancer (continued). "Here we find that Snail1 and Prrx1, which respectively associate with gain or loss of stem-like properties and with bad or good prognosis in cancer patients, are expressed in complementary patterns during vertebrate development and in cancer." (PMID 31712603, 2019). "The roles and underlying mechanism for PRRX1 in cancer pathogenesis and the origination of MET-type CSCs remain unknown." (PMID 30038266, 2018). "There is growing evidence that PRRX1 is highly expressed in certain cancers and is critically involved in human survival prognosis." (PMID 38448751, 2024). "Paired related homeobox 1 (PRRX1) is an inducer of epithelial-to-mesenchymal transition (EMT) in different types of cancer cells." (PMID 38978350, 2024). "Three public EMT/mesenchymal signatures generated independently from meta-analyses across cancer types were used to validate that the PRRX1 signature captures a subgroup with mesenchymal biology." (PMID 36968142, 2023). "We therefore evaluated the expression of a panel of epithelial (KRT5, 7, 8, 18, and CDH1), mesenchymal (VIM, FN1, SNAI1, TWIST1, COL1A1, and PRRX1), and cancer stem cell (ALDH1A2, ALDH7A1, CD44, and CCND1) markers in all samples." (PMID 36980717, 2023). "Other upregulated target genes include the Homeobox TF genes PRRX1 and PKNOX2, both of which have roles in mesenchyme development, while PRRX1 also promotes EMT in cancers." (PMID 35904801, 2022). "Distinct functions have been reported for the two isoforms of PRRX1 in certain cancers, as well as in human oligodendrocyte progenitor cells (hOPCs)." (PMID 34214250, 2022). "We compared the core promoter-mutated genes with altered gene expression to the cancer driver gene list and observed that the somatic-mutated TERT and PRRX1, and germline-mutated GAB2 were on the list." (PMID 35033028, 2022). "Fibroblast-specific PRRX1 depletion induces long-term and sustained complete remission of chemotherapy-resistant cancer in genetically engineered mice models." (PMID 35589735, 2022). "This study expands our knowledge of CAF biology by contributing an innovative cancer mouse model that recapitulates desmoplasia by inducing Prrx1 expression in fibroblasts." (PMID 35589735, 2022). "Myofibroblast-related gene sets were remarkably enriched in the Prrx1-high CAF subpopulation across all seven cancer types." (PMID 35589735, 2022). "The CAF subpopulation with Prrx1 as an mTF shows absolute dependence on Prrx1 expression, and conditional depletion of Prrx1 in fibroblasts in vivo induced and maintained CR of chemoresistant cancer." (PMID 35589735, 2022). "This study showed that conditional Prrx1 depletion in fibroblasts successfully induced CR in established chemoresistant cancers in vivo." (PMID 35589735, 2022). "The importance of Prrx1 in the pro-tumorigenic activity of CAFs was confirmed by cotransplanting cancer cells and CAFs into immunodeficient mice." (PMID 35589735, 2022). "The top 10 frequently affected cancer-associated genes are HIRA (OG), CSMD1 (TS), CDH13 (TS), PRRX1 (OG), FHIT (TS), MGAM (OG), TBL1XR1 (OG), RHOA (OG), FGF14 (TS), and CNTNAP2 (TS)." (PMID 35013466, 2022). "Although PRRX1 was found to mediate carcinoma cell invasion and metastasis by inducing the EMT, other studies found that the loss of PRRX1 results in the reversion of the EMT and the induction of the MET, favoring metastatic colonization." (PMID 35281030, 2022). "Our analysis of human HCC datasets indicated a direct correlation between PRRX1 and cancer-related processes, e.g. PI3K-Akt signaling pathway, focal adhesion, extracellular matrix, actin cytoskeleton activities and EMT." (PMID 34496784, 2021). "In accordance with other studies indicating the tight association between Prrx1 and cancer stem cells, previous study in GBM has reported Prrx1’s essential roles in GSC maintenance and tumorigenesis." (PMID 34131109, 2021). "The analysis was complemented with experiments to gain insight on the functional relevance of PRRX1 in this cancer type." (PMID 34496784, 2021).
cancer (continued). "Altogether, these findings suggest that modulating PRRX1 alters ZEB1/2 and is accompanied by various cellular phenotypes associated with cancer." (PMID 34496784, 2021). "Taken together, these data suggest that PRRX1 promotes cancer pathways and contributes to a suppressed metabolic gene program, as previously seen in HCC." (PMID 34496784, 2021). "Prrx1 is identified as a homeodomain transcription factor and involves multiple cancers progression via regulation of transcription activity." (PMID 34131109, 2021). "Targeting EMT inducers, such as Paired-related homeobox protein 1 (Prrx1), allows cancer cells to acquire properties of metastatic colonization and suggest that, for metastasis, the role of the EMT is context-dependent." (PMID 32218208, 2020). "Paired-related homeobox 1 (PRRX1) overexpression activates EMT in certain cancers, including those of the stomach, colorectum, pancreas or breast, and promotes a migratory and invasive phenotype." (PMID 32318352, 2020). "We therefore suggested that PRRX1‐induced EMT in cancer cells activated the metabolic reprogramming of FFAs to promote metastasis of SACC." (PMID 31657086, 2020). "This explains why there is a positive correlation between high levels of Prrx1 and better prognosis in cancer patients." (PMID 31712603, 2019). "Prrx1 needs to be downregulated in cancer cells to promote the reversion, and its downregulation implies an increase in stem cell properties that are also essential for metastatic growth." (PMID 31712603, 2019). "Here, we show that Snail1 and Prrx1 are expressed in a complementary manner during vertebrate development and in cancer patients." (PMID 31712603, 2019). "Like AIF1, PRRX1 expression strong correlated with its interacting partners, several of which were conserved across the four cancers." (PMID 26272668, 2015). "PRRX1, traditionally recognized as a transcription factor, plays essential roles in specification of mesodermal and neural crest lineages, as well as in the tumorigenesis and metastasis of cancer cells." (PMID 40114375, 2025). "PRRX1, a transcription factor, contributes to embryonic development and cancer invasiveness." (PMID 40683881, 2025). "Alternative splicing generates two isoforms of the transcription factor paired-related homeobox 1 (PRRX1): PRRX1a and PRRX1b, which may be regulated by mechanical pacing during cancer cell metastasis." (PMID 38397421, 2024). "PRRX1 mediates cancer cell invasion and metastasis by starting EMT." (PMID 36843929, 2023). "PRRX1 was more highly expressed in CAFs than in fibroblasts of normal tissues, and PRRX1 expression was strongly correlated with fibroblast-activation score in all six datasets from six organs, including cancer and normal tissues (lung, colon, pancreas, head and neck, ovary, and stomach)." (PMID 35589735, 2022). "One reason for the potential application of Prrx1 as an effective therapeutic target for anti-CAF drugs may be the key role of Prrx1-modulated CAF subset in cancer progression." (PMID 35589735, 2022). "It is plausible that Prrx1 may induce common mesenchymal programs in cancer cells, however, this requires further study." (PMID 35589735, 2022). "Indeed, the migration, invasion, and stemness of 168FARN cancer cells were significantly increased when cocultured with expressing MMTV-CAFs compared with cancer cells cocultured with Prrx1-deleted MMTV-CAFs." (PMID 35589735, 2022). "Next, we confirmed whether fibroblast-specific induction of PRRX1 expression promotes cancer progression." (PMID 35589735, 2022). "Finally, Prrx1 was reported as the mTF identified in CAFs that can serve as a potential therapeutic target to achieve CR of chemoresistant cancer." (PMID 35589735, 2022).